SPATA12 (spermatogenesis associated 12)
Synonyms: SRG5
Tractability: Antibody: the Human Protein Atlas places it where antibodies can reach.
Gene: Protein-coding gene on chromosome 3 (57,060,664 to 57,075,432, forward strand). Ensembl gene ENSG00000186451.
Subcellular location (Human Protein Atlas): Cytosol; Nucleoplasm; Plasma membrane
Gene Ontology:
Molecular function: protein binding
Genetic constraint (gnomAD): Loss-of-function variants: 0 observed, 0.31 expected, observed/expected ratio (o/e) 0, 90% interval 0 to 1.86. That is too few expected variants to judge how well the gene tolerates losing a copy. Missense variants: 219 observed, 239.53 expected, observed/expected ratio (o/e) 0.91, 90% interval 0.82 to 1.02. Synonymous variants: 85 observed, 94.36 expected, observed/expected ratio (o/e) 0.9, 90% interval 0.75 to 1.08.
Homologues: Orthologues: chimpanzee SPATA12 (97% identical), macaque SPATA12 (91% identical).
Diseases named in the same sentence as SPATA12 in open-access papers:
SPATA12 is named in the same sentence as 1 disease in open-access papers, as found by Europe PMC text mining. Sharing a sentence is not in itself a finding about the gene and the disease.
SPATA12 shares sentences with these, for which no sentence is quoted: cryptorchidism (1 paper).